ATAD3B (ATPase family AAA domain containing 3B)
Description:
May play a role in a mitochondrial network organization typical for stem cells, characterized by reduced mitochondrial metabolism, low mtDNA copies and fragmentated mitochondrial network. May act by suppressing ATAD3A function, interfering with ATAD3A interaction with matrix nucleoid complexes.
Synonyms: KIAA1273; TOB3; AAA-TOB3
Tractability: Antibody: UniProt places it where antibodies can reach, with high confidence; its Gene Ontology location is reachable by antibodies, with high confidence. PROTAC: ubiquitination databases record sites on it; its protein half-life has been measured.
Gene: Protein-coding gene on chromosome 1 (1,471,756 to 1,497,848, forward strand). Ensembl gene ENSG00000160072.
Subcellular location: Mitochondrion inner membrane
Subcellular location (Human Protein Atlas): Mitochondria; Acrosome
Pathways (Reactome):
Immune System: Neutrophil degranulation
Gene Ontology:
Molecular function: ATP binding; ATP hydrolysis activity
Biological process: mitochondrion organization
Cellular component: mitochondrion; ficolin-1-rich granule membrane; plasma membrane; secretory granule membrane; mitochondrial inner membrane
Genetic constraint (gnomAD): Loss-of-function variants: 57 observed, 61.68 expected, observed/expected ratio (o/e) 0.92, 90% interval 0.75 to 1.15. The synonymous counts are far from expectation, so gnomAD's model fits this gene poorly and the ratio says little. Missense variants: 946 observed, 806.15 expected, observed/expected ratio (o/e) 1.17, 90% interval 1.11 to 1.24. Synonymous variants: 419 observed, 347.42 expected, observed/expected ratio (o/e) 1.21, 90% interval 1.11 to 1.31.
Homologues: Orthologues: chimpanzee ATAD3B (75% identical), zebrafish atad3 (28% identical). Paralogues in human: ATAD3A (84% identical), ATAD3C (56% identical).
Diseases named in the same sentence as ATAD3B in open-access papers:
ATAD3B is named in the same sentence as 17 diseases in open-access papers, as found by Europe PMC text mining. Sharing a sentence is not in itself a finding about the gene and the disease. The quoted sentences say what the papers report.
breast carcinoma (4 papers, 2013 to 2019). "Our results indicate, for the first time, that over-expression of ATAD3B is also associated with significantly lower survival of post-menopausal breast cancer patients with ER+/HER2− tumors." (PMID 23818839, 2013). "Also, ATPase Family, AAA Domain Containing 3B (ATAD3B) was reported to significantly associate with poor survival in breast cancer patients." (PMID 28765560, 2017). "Even though more work is needed to firmly establish the role of ATAD3B in this subtype of breast cancer, our results demonstrate that SPINLONG is capable of producing experimentally testable hypotheses from large-scale deep sequencing data." (PMID 23818839, 2013). "In this study, we detected three mitochondrial proteins (CPS1, ATAD3A/ATAD3B, and ABHD11) and one lysosomal protein (cathepsin D) with different expressions in paclitaxel-resistant MCF7/PacR breast cancer cells compared to paclitaxel-sensitive MCF7 breast cancer cells." (PMID 31248089, 2019). "Accordingly, inhibition of the MAPK pathway leading to inactivation of myogenin or Myc could lead to down-regulation of ATAD3B and thus provide a putative therapeutic target for post-menopausal ER+/HER2− breast cancer patients." (PMID 23818839, 2013). "The survival analysis of the 777 responsive genes with 150 primary breast cancer tumors and in two independent validation cohorts indicated the ATAD3B gene, which does not have binding site within 20 kb of its TSS, to be significantly associated with poor patient survival." (PMID 23818839, 2013). "Furthermore, our results point to the direction that the non-genomic pathway, via ATAD3B, may play a role in resistance to anti- therapeutics in breast cancer." (PMID 23818839, 2013).
hepatocellular carcinoma (4 papers, 2022 to 2025). A malignant tumor that arises from hepatocytes. "ATAD3B, a mitochondrial membrane-bound protein, has been associated with tumorigenesis and suggested as a potential prognostic biomarker for hepatocellular carcinoma patients." (PMID 41155404, 2025). "In addition, the higher the expression level of ATAD3B in hepatocellular carcinoma compared with normal liver tissue, the lower the survival rate of patients." (PMID 40688112, 2025). "ATAD3B has been shown to be over-expressed in head and neck cancer and hepatocellular carcinoma." (PMID 35525914, 2022). "The association with ATAD3A and ATAD3B expression may be of interest since ATAD3 over-expression has been linked to the progression of head and neck cancer, lung adenocarcinoma, non‐Hodgkin's lymphoma, uterine cancer, cervical cancer, prostate cancer, glioma, and hepatocellular carcinoma." (PMID 35525914, 2022).
Cerebellar atrophy (3 papers, 2017 to 2022). Cerebellar atrophy is defined as a cerebellum with initially normal structures, in a posterior fossa with normal size, which displays enlarged fissures (interfolial spaces) in comparison to the foliae secondary to loss of tissue. "On the other hand, when ATAD3 gene rearrangements affected the ATAD3B/ATAD3C genes on one allele and the ATAD3A/ATAD3B genes on the other, late-onset encephalopathy with cerebellar atrophy, ataxia, and dystonia was seen as the clinical effect." (PMID 33113782, 2020).
colorectal cancer (1 paper, 2025). A primary or metastatic malignant neoplasm that affects the colon or rectum. "We used whole genome sequencing to capture information on gene targets that have mutations in the genomes of colorectal cancer and adjacent cancers and analyzed and screened high-frequency mutated genes (ATAD3B) and susceptibility genes (SH3BP1, C4orf54)." (PMID 40688112, 2025). "It is also worth noting that the role of this gene may be different in different cancers, and there are currently no reports of ATAD3B gene research in colorectal cancer, so this gene can be used as a target gene for further research." (PMID 40688112, 2025).
pontocerebellar hypoplasia (1 paper, 2017). Pontocerebellar hypoplasias (PCH) are a rare heterogeneous group of diseases characterized by hypoplasia and atrophy and/or early neurodegeneration of the cerebellum and pons. "The identification of five pontocerebellar hypoplasia families with different ethnicities and ATAD3B/ATAD3A gene fusions suggests ATAD3 defects could underlie a significant portion of the remaining cases lacking a molecular diagnosis, especially those with associated cortical abnormalities." (PMID 28549128, 2017).
cancer (9 papers, 2013 to 2025). A tumor composed of atypical neoplastic, often pleomorphic cells that invade other tissues. "Some Class II genes that we found, such as SLC19A1 and ATAD3B, have been recently reported to associate with cancer outcomes." (PMID 28765560, 2017). "ATAD3A is ubiquitously expressed in all tissues from very early embryonic stages to adulthood, while ATAD3B is specifically expressed in human embryonic stem cells and is re-expressed in certain types of cancers." (PMID 35093151, 2022). "KIAA0090, ATAD3B, TRIM27 and DMTF1, regulated by hypo-methylated sites, were also associated with cancer." (PMID 33549049, 2021). "It was shown that ATAD3B is expressed in pluripotent embryonic stem cells and in cancer cells where it negatively regulates ATAD3A function." (PMID 31248089, 2019). "ATAD3B was expressed in cancer cell, and may related with tumorigenesis, proliferation and chemoresistance." (PMID 33549049, 2021). "Considering that ATAD3B is a potential stem cell-specific marker expressed in certain cancer types, it is suggestive, therefore, that ATAD3B may be a putative target to complement anti-cancer therapeutics." (PMID 33113782, 2020). "Several studies with human cancer cells pointed out a role of ATAD3A and ATAD3B in tumor progression." (PMID 23372768, 2013). "In addition to 4 same genes (KIAA0090, ATAD3B, TRIM27 and DMTF1) with LUSC-C1, ACP1 and SH3YL1 also played important roles in cancer." (PMID 33549049, 2021). "In this case, anti-cancer therapies co-targeting ATAD3A and ATAD3B would likely be required, though may give rise to an encouraging synergistic effect leading to greater therapeutic efficacy." (PMID 33113782, 2020).
tumor (6 papers, 2013 to 2025). "Whole genome sequencing revealed that ATAD3B has a mutation frequency of 7.69% in tumor samples." (PMID 40688112, 2025). "In order to find out whether the survival association of ATAD3B expression is correlated with disease progression, we performed a Cox survival analysis for ATAD3B with tumor stage as a control variable." (PMID 23818839, 2013). "ATAD-3 and its homologs in other species (ATAD3A, ATAD3B) have been described as mitochondrial proteins with roles in tumor progression." (PMID 27506200, 2016). "This analysis indicates that ATAD3B has predictive power independent from tumor stage (Cox )." (PMID 23818839, 2013). "A set of genes including PRPF38A, RIOK3, QSER1, PSMC3IP, ATAD3B, MGC12982, and C20ORF27 were significantly overexpressed in HCC-R tumor tissue with fold changes ≥4 (P = 0.001 to 0.0001)." (PMID 24377043, 2013).
ATAD3B also shares sentences with these, for which no sentence is quoted: Ataxia (2 papers); Dystonia (2); cervical cancer (1); Encephalopathy (1); glioma (1); head and neck cancer (1); lung adenocarcinoma (1); prostate carcinoma (1); schizophrenia (1); uterine cancer (1).